G3BP1 (G3BP stress granule assembly factor 1)
Diseases named in the same sentence as G3BP1 in open-access papers (continued):
Sharing a sentence is not in itself a finding about the gene and the disease.
infection (continued). "In this report, we show that during infection, RABV promotes the formation of cytoplasmic SGs that contain TIA-1, G3BP1 and PABP." (PMID 27749929, 2016). "Immunofluorescence microscopy revealed that, following infection, TIA-1 translocated from the nucleus to the cytoplasm and formed aggregates co-localizing with G3BP1 (first and second column), indicating that SGs are formed in RABV-infected cells." (PMID 27749929, 2016). "Like G3BP1, G3BP2 is important for SG formation and is sequestered by chikungunya virus nsP3 to disassemble SGs late in infection." (PMID 27147742, 2016). "Taken together, these data indicate that G3BP1, G3BP2 and CAPRIN1 interact with DENV-2 gRNA and sfRNA during infection." (PMID 24992036, 2014). "In order to investigate a link between IFN-mediated antiviral activity and that of G3BP1, G3BP2 and CAPRIN1, cells depleted of these three proteins were pretreated with IFN-β before infection with DENV-2 NGC." (PMID 24992036, 2014). "We overexpressed G3BP1 in PK15 cells infected with PCV2 and extracted cytoplasmic and nuclear proteins to determine whether G3BP1 influenced the localization of Cap and Rep proteins in PCV2 during the later stages of infection." (PMID 39940851, 2025). "Interestingly, during the course of infection, an increasingly strong colocalization was observed between IE180 and G3BP1 in the nucleus both in PK-15 and Vero E6 cells, while G3BP1 was only observed in the cytoplasm in mock-infected cells." (PMID 40145738, 2025). "An indirect immunofluorescence assay was employed to ascertain the localization of G3BP1, a core component of SGs, to the SVA-N protein, with a view to determine whether SVA infection is responsible for SGs formation." (PMID 40849899, 2025). "A murine norovirus (MNV) infection was reported to inhibit SG formation, but foci containing G3BP1 but not eIF3B were observed near the viral replication sites." (PMID 40548742, 2025). "While the N protein eventually controls stress granules via its G3BP1/2 interaction, NSP3 binding to FMPRs could interfere with stress granule formation and antiviral activities early during infection." (PMID 38177924, 2024). "In this study, we observed a marked increase in G3BP1+ cytoplasmatic aggregates in VZVeGFP-ORF23-infected NSPHs, suggesting active cellular stress upon sustained NSPH infection (i.e. 7 days post-infection)." (PMID 39351233, 2024). "At 12, 24, and 36 h after infection, viral titers were more than 10-fold lower in the G3BP1 overexpression group than in the non-overexpression group." (PMID 38690262, 2024). "To deepen these observations, we followed the distribution of N and S proteins in the cytosolic and membrane fractions of infected cells KD or not for G3BP1/2 at 24 hpi, after several rounds of infection." (PMID 38245532, 2024). "Our examination of the role of G3BP1/2 in SARS-CoV-2 at early times of infection (10 hpi) did not reveal any consistent impact on the intracellular level of gRNA, nor on the level of S and N proteins." (PMID 38245532, 2024). "Interestingly, the SL-I of ZIKV can interact with proteins related to stress granules, such as Caprin-1, G3BP1, G3BP2 and USP10, to assess the success of infection." (PMID 36982407, 2023). "Our results show an important role of G3BP1 in regulating IFN production during VHSV Ia infection and cells lacking G3BP1 produced higher levels of IFN and reduced viral titers." (PMID 36851680, 2023). "We observed distinct G3BP1 puncta in the late stages of infection (36–48 h post infection (hpi)) in all three fish cell lines in contrast to the diffuse G3BP1 distribution in the non-infected cells." (PMID 36851680, 2023). "Moreover, it has been shown that the knockdown of G3BP1 impairs RSV replication, even if infection prevents SGs assembly." (PMID 37490507, 2023). "For initiation of infection, G3BP1 facilitates CHIKV, but not to SFV, translation of genomic RNA by enriching translation factors at cytopathic vacuoles." (PMID 36851663, 2023).
infection (continued). "The infection of IFNβ promoter or MX1 promoter luciferase transfected cells demonstrated a 3-fold and 4-fold increase, respectively, in both IFNβ and MX1 promoter activity with VHSV Ia infection in G3BP1 KD cells compared to WT RTgill cells." (PMID 36851680, 2023). "Cells lacking G3BP1 showed a decrease in phosphorylated eIF2α implicating that G3BP1 is required for the phosphorylation of eIF2α during infection." (PMID 36851680, 2023). "G3BP1 mRNA is reduced when TDP43 protein levels are low, as we found during productive infection in neurons infected with KOS, suggesting this could be a potential mechanism utilized by HSV-1 to control the host antiviral response." (PMID 36769256, 2023). "The infection of cells with VHSV Ia incapable of replicating lacked G3BP1 puncta and as expected there was no accumulation of viral proteins." (PMID 36851680, 2023). "We found that infection with SARS-CoV-2 S clade induces the formation of G3BP1-positive stress granules in Vero cells, but not in Calu-3 cells." (PMID 36081788, 2022). "The specific siRNA targeting G3BP1 was transfected into Vero cells, followed by PEDV infection." (PMID 35859736, 2022). "Additionally, there was no apparent difference in enterovirus replication kinetics and host translation shutoff in high MOI infections, indicating potential functional coordination between TDRD3 and G3BP1 at the level of virus infectivity." (PMID 35085371, 2022). "While not tested in the context of infection, this model is consistent with studies demonstrating interactions between N and M, G3BP1 and G3BP2 within stress granules, and phosphorylated N and nsp3 to promote the synthesis of viral RNA." (PMID 35728038, 2022). "We found that transfection of poly I:C (a dsRNA mimic) or infection with the R296T mutant induced the formation of G3BP1-positive/TIA1-negative RNase L-dependent bodies (RLBs) in WT cells and PKR KO cells, whereas infection with the K287T mutant induced RLBs in PKR KO cells." (PMID 34237110, 2021). "Indeed, infection with EMCV-Lpro L92A, resulted in cleavage of eIF4G, as well as all other Lpro substrates (i.e. MAVS, TBK1, NF-κB p65 and G3BP1)." (PMID 32667958, 2020). "Analysis of earlier time points at 2, 4, 6 or 8h post infection confirmed this with complete absence of G3BP1 and eIF3B positive SGs during MNV infection." (PMID 31905230, 2020). "Similarly, during infection of the recombinant SINV mCherry.capsid, the virus capsid redistributed with YBX1 and TIA1 and also with VCP and G3BP1 into a single perinuclear granule." (PMID 31905741, 2019). "Since the CRISPR knockout of G3BP1 was observed to completely inhibit infection, we utilized RNAi-mediated suppression of G3BP1 to identify how MNV may require G3BP1 for replication." (PMID 31213553, 2019). "The production of viral positive sense RNA was reduced to background levels in the absence of G3BP1, comparable to levels observed when the 2CMC was present during the infection." (PMID 31403400, 2019). "The levels of G3BP1 mRNA were comparable between mock-infected and FMDV-infected cells, regardless of post-infection times, suggesting that the reduction of G3BP1 protein abundance is not due to decrease in G3BP1 mRNA expression." (PMID 29887867, 2018). "In this study, we found that infection of PRRSV strain WUH3 (genotype 2 PRRSV) induced stable formation of robust SGs in MARC-145 cells, as demonstrated by the recruitment of marker proteins of SGs, including TIA1, G3BP1, and eIF3η." (PMID 28421170, 2017). "In PRRSV-infected cells, cytoplasmic granules containing SG marker proteins TIA1 or G3BP1 were not seen at 6 h post-infection (hpi) (data not shown), but they began to occur at 12 hpi and still existed at 48 hpi." (PMID 28421170, 2017). "However, late in infection, DDX3 and G3BP1 localize with the HCV core protein around LDs in order to initiate viral particle assembly." (PMID 27367717, 2016).
infection (continued). "The quantification of the number of cells displaying G3BP1 foci did not increase significantly during infection." (PMID 27147742, 2016). "Finally, the infection with Sindbis virus (SINV), another alphavirus, induces the assembly of G3BP1 aggregates, which interact with nsP2, nsP3 and nsP4." (PMID 27367717, 2016). "Since G3BP1, G3BP2 and CAPRIN1 had previously been determined to be critical regulators of stress granules (SG) assembly, another aspect of the cellular response to infection, we examined SG formation in infected cells and upon IFN treatment." (PMID 24992036, 2014). "To further test this hypothesis and determine the importance of this mechanism during infection and for viral evasion of the IFN response, we constructed mutant DENV-2 replicons unable to sequester G3BP1, G3BP2 and CAPRIN1." (PMID 24992036, 2014). "Our prior studies demonstrate a strong correlation between G3BP1 ADP-ribosylation and SG assembly: G3BP1 ADP-ribosylation increases under conditions when stress granules form, whereas this ADP-ribosylation reduces upon infection when the MAR-degrading nsP3 macrodomain inhibits SG assembly." (PMID 41067892, 2025). "Interestingly, G3BP1-positive puncta were not readily detected in either rWT- or rH234A-infected cells (N positive, red), indicating that neither rWT nor rH234A infection triggers evident SG formation." (PMID 40838727, 2025). "Interestingly, the L protein of EMCV, which similarly suppresses formation of canonical SGs late in infection, also abrogated the interaction between eIF4GI and G3BP1, although this protein is not a protease and thus cannot cleave eIF4GI." (PMID 40875754, 2025). "Additionally, we observed that the N protein hijacks G3BP1 with viral dsRNA at sites of active viral replication at early infection, where no other SG proteins, such as eIF4A, accumulate, suggesting the formation of proviral assemblies involving G3BP1." (PMID 39638802, 2024). "In addition, infection with some PEDV strains induces transient SG formation, with the virus subverting stable SG formation by inducing caspase-8 mediated G3BP1 cleavage or downregulating G3BP1 expression via the viral papain-like protease." (PMID 39445805, 2024). "Additionally, SGs do not form during infection with severe acute respiratory syndrome coronavirus 2 (SARS-CoV-2) because the nuclear capsid protein (NP) of SARS-CoV-2 targets G3BP1 to prevent SG formation." (PMID 38690262, 2024). "Unlike RNA viruses, the role of G3BP1 during infection with DNA viruses is poorly understood." (PMID 36851663, 2023). "Subsequently, we tested the integrity of G3BP1 during ASFV infection and found that an approximately 40 kDa cleavage product (designated G3BP1-C) could be detected after pS273R was expressed from 8 hours post infection (hpi) onward." (PMID 37209818, 2023). "Indeed, we previously demonstrated that although feline calicivirus (FCV) disrupts the assembly of SGs by inducing G3BP1 cleavage through its 3C-like protease, infection with the related murine norovirus (MNV) has no impact on G3BP1 integrity." (PMID 35098996, 2022). "To test if G3BP1 overexpressing cells are resistant to infection at early stages of virus attachment and penetration or if viral replication is inhibited by G3BP1 at later stages of infection, we conducted an infection time course in 293A[EGFP-G3BP1] and control 293A[EGFP] cells." (PMID 36534661, 2022). "This suggests that both DDX3X and G3BP1 are required for IAV–ΔNS1–induced SGs and led us to hypothesize that disrupting expression of Ddx3x or G3bp1 might restore NLRP3 activation after IAV–ΔNS1 infection." (PMID 33766561, 2021). "Infection of cells with porcine reproductive and respiratory syndrome virus (PRRSV) induces the formation of SGs, which are associated with the viral replication complex (VRC); however, G3BP1 does not play a role in PRRSV replication." (PMID 34526993, 2021).
infection (continued). "Similarly, lack of G3bp1 expression in immortalized BMDMs (G3bp1−/− iBMDMs) reduced the formation of SGs after IAV–ΔNS1 infection." (PMID 33766561, 2021). "Thus, the condensation of G3BP1 during infection does not seem responsible for preventing SG formation by sequestering G3BP1, as opposed to what happens during alphavirus replication." (PMID 31905230, 2020). "The percentage of infected cells containing G3BP1 puncta was found to be between 10 and 25% and this percentage remained unchanged over the course of infection, with no statistical difference between the percentages of cells containing puncta at any time point." (PMID 32422883, 2020). "HCV-JFH1 infection redistributes several SG components, including G3BP1, ataxin-2 (ATX2), and poly(A)-binding protein 1 (PABP1), to the HCV replication complex (RC), and co-opts G3BP1 to mediate efficient viral replication by interaction with NS5B and the 5′ end of the HCV minus-strand RNA." (PMID 31037644, 2019). "To define the precise role of G3BP1 in the early stages of the virus life cycle, we used strand-specific RT-qPCR to quantify the levels of viral positive and negative sense RNA in WT and ΔG3BP1 cell lines following infection with MNV." (PMID 31403400, 2019). "However, the reason why eIF3 is recruited to PRRSV-induced SGs late in infection rather than early, like G3BP1, remains a question for further study." (PMID 28421170, 2017). "Therefore, unlike FCV, MNV infection does not impair the ability of cells to form SGs, at least in the culture system examined here, and we propose that this is due to the absence of G3BP1 cleavage." (PMID 27147742, 2016). "Interestingly, G3BP1 cleavage does not contribute to the disassembly of SGs formed following infection by TMEV, which is in contrast to EMCV." (PMID 27999393, 2016). "The infection with Cricket paralysis virus (CrPV), a member of Dicistroviridae family, prevents the aggregation of Rox8 and Rin, Drosophila SG marker homologs of TIA-1 and G3BP-1, respectively, even in the presence of various stressor, such as arsenite, pateamine A or heat shock." (PMID 27367717, 2016). "However, ISRIB treatment had no impact on the accumulation of G3BP1 granules during MNV infection." (PMID 31905230, 2020). "Therefore, the presence of an alanine in the murine G3BP1 could explain the lack of cleavage by the MNV NS6Pro during infection and, consequently, the ability of MNV-infected cells to assemble SGs in response to arsenite treatment, at least in J774 cells." (PMID 27147742, 2016). "Despite the infection of SARS-CoV-2 leading to the disruption of SG assembly, we found that SARS-CoV-2 3CLpro or PLpro did not cleave G3BP1." (PMID 37049786, 2023). "Infection rates were the same between EGFP-G3BP1 and control EGFP overexpressing cells, indicating that virus attachment and penetration was not affected by G3BP1 overexpression." (PMID 36534661, 2022). "Although G3bp1−/− iBMDMs formed fewer SGs after IAV–ΔNS1 infection, we still observed SGs containing DDX3X but not G3BP1 in these cells." (PMID 33766561, 2021). "As with avSG formation in RNase L-activated cells, G3BP1 interacted with Rig-I and PKR in avSG core only during infection, and OAS and RNase L localized to avSGs but did not interact with G3BP1." (PMID 32295917, 2020). "Infection with EMCV-Lpro, but not EMCV-Lpro C51A, resulted in the rapid cleavage of eIF4G (from 4 hpi onwards) and the cleavage of G3BP1 (from 6 hpi onwards)." (PMID 32667958, 2020). "TIA-1 is not sequestered in DNA factories; however, infection with a VV mutant lacking E3L, which activates PKR, induces aggregates that contain TIA-1, eIF3b, G3BP1 and USP10, called antiviral granules (AVGs), given that they restrict viral replication." (PMID 27367717, 2016).
infection (continued). "Overall, we show that SGs assembly during infection does not modulate viral replication and is uncoupled from IIR activation, while FMDV actively cleaves G3BP1 by a 3Cpro-mediated mechanism to promote their disassembly, suggesting a potential antiviral role for persistent SGs." (PMID 42275447, 2026). "Cells lacking both G3BP1/G3BP2 do not support replication of the Old World alphaviruses but do support replication of the New World encephalitic alphaviruses, indicating a virus-specific importance of G3BP1 for infection." (PMID 36851663, 2023). "Furthermore, while infection with another norovirus model, Feline Calicivirus (FCV) disrupts the assembly of SGs by inducing G3BP1 cleavage, MNV infection has no impact on G3BP1 integrity." (PMID 31905230, 2020). "Interestingly, in the absence of infection, we observed endogenous proteolysis of proteins known to be cleaved by enteroviruses, including DDX6, HNRPM, EIF5B, G3BP1, and eIF4G1/2." (PMID 38918600, 2024). "Overall, our results support a model in which MNV infection results in a large cytoplasmic redistribution of G3BP1 partners which, together with the absence of PKR-dependent phosphorylation of eIF2α, could provide the basis for evasion of SG assembly during infection." (PMID 31905230, 2020).